TECTA (tectorin alpha)
Diseases named in the same sentence as TECTA in open-access papers:
TECTA is named in the same sentence as 26 diseases in open-access papers, as found by Europe PMC text mining. Sharing a sentence is not in itself a finding about the gene and the disease. The quoted sentences say what the papers report.
deafness (30 papers, 2012 to 2025). An inherited or acquired condition characterized by the complete loss of the ability to hear from one or both ears. "The variant c.5999G > A (p.Gly2000Glu) in TECTA, in a heterozygous state, co-segregated with the deafness phenotype in the extended family." (PMID 40583560, 2025). "Missense mutations in TECTA that have been reported thus far are associated with the dominant subtype, whereas those leading to recessive deafness are are truncating variants, most likely representing loss-of-function mutations." (PMID 40583560, 2025). "As summarized above, in this study, rare pathogenic variants were identified in four separate deafness-associated genes, TECTA, MYO7A, HGF, and POU3F4, which have distinct expression profiles and functions in the inner ear." (PMID 33976695, 2021). "It has been shown that mutations in Otogelin and α-Tectorin impair otolith seeding, and mutations in their human orthologs OTOG and TECTA cause deafness." (PMID 33326993, 2021). "TECTA was the causal gene of autosomal recessive deafness (type 21), and 40 pathogenic variants in this gene have been identified in ClinVar." (PMID 32682410, 2020). "The similarities between the clinical characteristics of HL in patients with OTOA and TECTA gene mutations reflect the mechanism of deafness caused by TM impairment." (PMID 31527525, 2019). "In humans, mutations in OTOG and TECTA cause deafness and, in some cases, vestibular dysfunction, making the einstein and rolling stones zebrafish mutants new models of these disorders." (PMID 25758224, 2015). "Mutations in the human TECTA gene can cause either dominant (DFNA8/12) or recessive (DFNB21) forms of deafness." (PMID 25758224, 2015). "Whilst the effects of TECTA mutations are reported to be non-syndromic and only cause deafness, subtle sub-clinical phenotypes cannot be excluded." (PMID 24363064, 2014). "Among the five candidate mutations, T7511C in MT-TS1 and p.C1509G in TECTA have been reported to be associated with non-syndromic deafness in previous studies." (PMID 23767834, 2013). "Mutations in the TECTA gene are therefore often linked to deafness." (PMID 29371927, 2017). "It was suspected that variants in few genes like STRC, GJB2, SLC26A4, OTOG or TECTA may explain the hearing loss for the majority of individuals in our cohort as is the case in many other world populations for the individuals with moderate to severe deafness." (PMID 32681043, 2020). "We analyzed the influence of the four selected reference genes on the expression profile of OTOF and TECTA, two deafness-related genes." (PMID 38474154, 2024). "In this study, we performed targeted NGS in three Pakistani consanguineous families and identified novel variants in TECTA and POU3F4 and previously reported variants in MYO7A and HGF as the pathogenic causes for prelingual, severe-to-profound deafness." (PMID 33976695, 2021). "Targeted NGS of 127 hearing loss‐related genes was carried out in the 9 probands, which allowed us to detect 5 reported and 5 novel variants in 6 distinct deafness genes including CDH23, GIPC3, MYO7A, TRIOBP, TECTA, and OTOF." (PMID 32864763, 2020). "SR-285 carried three candidate variants of known deafness genes (p.Q445R in GRHL2, p.T1321S in TECTA, and p.S2161F in MYO15A); only one mutation, p.S2161F in MYO15A, was shared with an affected sibling." (PMID 23865914, 2013). "Mutations in nine deafness genes (COCH, KCNQ4, MYO7A, TECTA, CRYM, POU3F4, EYA1, mitochondrial tRNA(Lys) m.8296A>G, mitochondrial tRNA(Ser) m.7445A>G) were not identified in any patients." (PMID 22384008, 2012). "According to the HGMD database, about 89.0% of the variants in CDH23 gene, 85.0% of the variants in TECTA gene, and 69.4% of the variants in OTOF gene are missense mutations, which reminds us that the missense mutations in deafness causative genes should be given more consideration." (PMID 36597107, 2023).
deafness (continued). "The GJB2 and TECTA genes cause recessive non-syndromic deafness, and their variations have never been reported in TS-ANSD." (PMID 36837553, 2023). "Interestingly, this female with autism and a normal IQ was also homozygous for another deleterious variant (p.N687K, rs139165033, gnomAD European allele frequency = 0.003165) affecting TECTA, a SFARI gene associated with autism and deafness." (PMID 30675382, 2019). "Two of the mice created in this study, the TectaC1837G/+ and the TectaC1619S/+ mice, have missense mutations that involve the loss of cysteine residues and were generated as models for TECTA mutations that are reported to cause progressive, as opposed to stable, forms of human deafness." (PMID 24363064, 2014). "Twelve homozygous mutations in known deafness genes, of which eight are novel, were identified in 12 families: MYO15A-p.Q1425X, -p.S1481P, -p.A1551D; LOXHD1-p.R1494X, -p.E955X; GIPC3-p.H170N; ILDR1-p.Q274X; MYO7A-p.G2163S; TECTA-p.Y1737C; TMC1-p.S530X; TMPRSS3-p.F13Lfs*10; TRIOBP-p.R785Sfs*50." (PMID 23226338, 2012). "Three deafness-related PSGs might also perform roles in balance and spatial orientation: PDZD7 and GRXCR2 are involved in morphogenesis of the sensory hair cells (‘stereocilia’) in the inner ear, and TECTA encodes a key protein of the tectorial membrane in which the stereocilia are embedded." (PMID 38066641, 2023). "TMPRSS3, MYO15A, GJB2, SLC26A4 were found to be responsible for deafness in autosomal recessive or sporadic families, while TECTA, WFS1, MYH9, EYA1, COL4A5 and COL11A1 were identified as the responsible genes for deafness in autosomal dominant families." (PMID 23967202, 2013). "TECTA, WFS-1, MYH9, EYA1, COL4A5, COL11A1 were identified as the responsible genes for deafness in autosomal dominant families." (PMID 23967202, 2013). "As an example of target genes, we selected the two well-known deafness genes OTOF and TECTA." (PMID 38474154, 2024). "Hotspot mutations in the deafness-associated genes are not uncommon, and have been reported for KCNQ4, ACTG1, WFS1, and TECTA." (PMID 32486382, 2020). "Defects in TECTA are cause of both dominant (DFNA8/12, OMIM 601543) and recessive (DFNB21, OMIM 603629) forms of deafness, and absence of TECTA gene is responsible for Jacobsen syndrome (OMIM 147791), a contiguous gene deletion syndrome involving terminal chromosome 11q." (PMID 23936151, 2013).
hearing loss (30 papers, 2011 to 2025). "We reviewed all reported TECTA variants associated with hearing loss, compared and contrasted their outcomes, and included the inheritance models and auditory profiles of carriers." (PMID 40583560, 2025). "Two forms of hearing loss are linked to TECTA mutations: DFNA8/12 (autosomal dominant) and DFNB21 (autosomal recessive)." (PMID 40583560, 2025). "Here, we report putatively novel variants in the genes MYO15A, MYO7A, and TECTA identified through genetic panel testing in children with hearing loss at birth or in early childhood." (PMID 39062005, 2024). "Missense variants in the α-tectorin gene (TECTA) cause autosomal dominant (DFNA8/A12) non-syndromic hearing loss (ADNSHL) and account for a considerable number of ADNSHL cases." (PMID 37927186, 2023). "Pathogenic variants in genes that affect the tectorial membrane function, such as COLL11A2 and TECTA, are thus likely causing hearing loss with near-normal speech-in-noise performance and normal loudness growth." (PMID 36360160, 2022). "Consistently, a similar type of hearing loss has also been associated with many variants in TECTA, MYO7A, HGF, and POU3F4 in previous reports." (PMID 33976695, 2021). "The TECTA gene is linked to AD non-syndromic hearing loss and disease-causing variants in the TECTA gene are the most frequent cause of dominant hearing loss." (PMID 32937936, 2020). "TECTA is well known as a causative gene for autosomal dominant mid-frequency hearing loss observed in various populations." (PMID 31554319, 2019). "Many mutations in the α-tectorin gene (TECTA) have been reported to cause non-syndromic hearing loss (NSHL) in either a dominant or recessive inheritance pattern." (PMID 30935366, 2019). "It was previously reported that WRSs in patients with TECTA mutations are superior to those in individuals with age-related hearing impairment presenting with the same levels of hearing loss." (PMID 28946916, 2017). "The DFNA8/12 mutations in TECTA, which cause dominant hearing loss, all substitute highly conserved amino acids." (PMID 24586623, 2014). "As one of causative genes of ADNSHL, TECTA mutations have been identified in various types of hearing loss, age of onset, progression and frequency involvement in various populations." (PMID 25008054, 2014). "We further studied the genotype-phenotype correlation of mutation in TECTA gene with control subjects from the same family with normal hearing and confirmed that mutation in TECTA gene is responsible for the hearing loss in this Mongolian family." (PMID 25008054, 2014). "All TECTA mutations described to date have shown significant genotype-phenotype correlation with hearing loss." (PMID 25008054, 2014). "In this study, we examined the genetic basis of ADSHNL in a Mongolian family with hereditary hearing loss by exon-capture sequencing of known genes associated with hearing loss and identified a novel mutation in TECTA gene." (PMID 25008054, 2014). "The majority of missense mutations that cause hearing loss related to TECTA reside in the zona pellucida and zonadhesin domains of the gene." (PMID 24816743, 2014). "We then confirmed the presence of the novel missense mutations c.6016 G > T (p.Asp2006Tyr) of the TECTA gene in exon 20 of the rest of all 13 participated subjects with hereditary hearing loss." (PMID 25008054, 2014). "The TECTA gene encodes the α-tectorin protein in the striated sheet matrix, whereas the TM is an acellular gelatinous structure that contacts the hair cells in the organ of Corti; therefore, mutation of the TECTA gene leads to hearing loss." (PMID 24586623, 2014). "Despite several reports indicating an association of TECTA mutations with hereditary hearing loss, the precise molecular mechanism remains unclear." (PMID 30935366, 2019).
hearing loss (continued). "In this study, we performed exon capture sequencing of a Mongolian family with hereditary hearing loss and identified a novel mutation in TECTA gene, which encodes α -tectorin, a major component of the inner ear extracellular matrix that contacts the specialized sensory hair cells." (PMID 25008054, 2014). "TECTA has been identified as autosomal dominant (DFNA8/12) and autosomal recessive (DFNB21) causes of non-syndromic hereditary hearing loss." (PMID 39062005, 2024). "HL associated with the MYO6, TECTA, and COCH genes was identified in patients with mild hearing loss." (PMID 38790200, 2024). "COL11A1: ID8 has hearing loss, left-sided SSCD, and heterozygous missense variants in two genes known for AD nonsyndromic hearing loss, namely COL11A1 (MIM 120280; 1p21.1) and TECTA (MIM 602574; 11q23.3)." (PMID 33924653, 2021). "TECTA gene, located on 11q22‐q24, has been implicated both in autosomal dominant (DFNA) and autosomal recessive (DFNB) forms of nonsyndromic hearing loss." (PMID 32864763, 2020). "The TECTA gene is known as a causative gene for DFNA8/DFNA12 and DFNB21 hearing loss in humans, and SLC26A4 is related to autosomal recessive hearing loss." (PMID 25008054, 2014). "Mutations of the genes encoding OTOG (otogelin, DFNB18B), OTOGL (otogelin-like, DFNB84B), and TECTA (α-tectorin, DFNA8/12, DFNB21) have been associated with hearing loss in humans, with occasional reports of vestibular hyporeflexia or vertigo in patients with OTOG or TECTA defects." (PMID 35444606, 2022). "Although rare variants in TECTA, OTOG, and OTOGL have been associated with hearing loss, none of the variants identified in the current meta-analysis associate with hearing loss, identified by ICD-10 codes H90 and H91, nor any rare variants in the six GWAS candidate genes." (PMID 34620984, 2021). "A novel missense mutation c.6016 G > T (p.Asp2006Tyr) of TECTA gene is a characteristic TECTA-related mutation which causes autosomal dominant nonsyndromic hearing loss." (PMID 25008054, 2014). "Novel mutations were identified in multiple other genes - CDH23, MYO15A, WFS1, and TECTA - that are known to be responsible for hearing loss but are not routinely evaluated, largely because of their size." (PMID 21917145, 2011). "Unlike dominant TECTA variants, which are associated with milder hearing loss DFNA8/12 (MIM 601543), the recessive TECTA variants often result in prelingual, severe-to-profound hearing loss (DFNB21, MIM 603629)." (PMID 33976695, 2021).
autosomal dominant nonsyndromic hearing loss (6 papers, 2012 to 2025). Autosomal dominant form of nonsyndromic deafness. "Mutations in the TECTA gene have been reported to be responsible for autosomal dominant non-syndromic hearing impairment and a recessively inherited disorder of sensorineural pre-lingual non-syndromic deafness." (PMID 29670130, 2018). "This study documents a novel missense mutations c.6016 G > T (p.Asp2006Tyr) of the TECTA gene that causes autosomal dominant nonsyndromic hearing loss in a Mongolian family." (PMID 25008054, 2014). "Moreover, proband 43 (but not her unaffected sister) displayed a variant of uncertain significance (VUS) in TECTA, which is associated with autosomal dominant deafness (DFNA8/12) and may contribute to her HI." (PMID 34148116, 2022). "In our study, skipping of exon 20 in TECTA resulted in an in-frame deletion of 83 amino acids in the TECTA protein, leading to protein misfolding and autosomal dominant deafness." (PMID 40583560, 2025). "TECTA-related deafness can be inherited as autosomal-dominant nonsyndromic deafness (designated DFNA) or as the autosomal-recessive version." (PMID 24586623, 2014). "Carcinoembryonic antigen-related cell adhesion molecule 16 (CEACAM16), an adhesion protein concentrating at the top of OHC stereocillia, interacts with TECTA and mutation of CEACAM16 results in autosomal dominant nonsyndromic deafness (ADNSHL) at the DFNA4 locus." (PMID 22942697, 2012).
age-related hearing impairment (2 papers, 2017 to 2019). "The hearing loss progression observed in the patients with TECTA mutations might reflect presbycusis." (PMID 31554319, 2019). "The HL progression observed in the patients with TECTA mutations might reflect presbycusis, as the HL deterioration rate was comparable with that of normal hearing controls." (PMID 31554319, 2019). "The HL progression (0.3 dB/year) observed in patients with TECTA mutations appears to reflect presbycusis, as the HL deterioration rate was comparable with that of normal hearing controls, suggesting that TECTA mutations do not accelerate HL deterioration." (PMID 31554319, 2019). "In Family 5, the lack of TECTA mutation in the father (of proband, II-1) with hearing loss, suggests that his hearing loss may be due to other causes, such as presbycusis." (PMID 28946916, 2017).
Jacobsen syndrome (2 papers, 2013 to 2025). A multiple congenital anomaly/intellectual disability contiguous gene syndrome caused by partial deletion of the long arm of chromosome 11. "Mutations in TECTA are associated with autosomal dominant (DFNA8/12) and autosomal recessive (DFNB21) nonsyndromic hearing loss, as well as with Jacobsen syndrome." (PMID 40901670, 2025).
age (1 paper, 2015). A temporal measurement of the time period elapsed since an identifiable point in the life cycle of an organism. "Genes that encode components of the otoconial membrane, such as OTOG or TECTA, might be good candidates for genetic predisposition to this disorder or for understanding age-related vestibular dysfunction." (PMID 25758224, 2015).
cone-rod dystrophy (1 paper, 2022). Inherited retinal dystrophies that belong to the group of pigmentary retinopathies. "In three of the USH cases, additional variants in genes for non-syndromic HI (OTOG, TECTA) or ABCA4-related VI (Stargardt disease, cone-rod dystrophy, and RP) may modify/aggravate the phenotype (left)." (PMID 34148116, 2022).
melanoma (1 paper, 2020). A malignant, usually aggressive tumor composed of atypical, neoplastic melanocytes. "In addition, both GRIN2A and TECTA were among the most intolerant genes according to the RVIS (Residual Variation Intolerance Score), indicating that the variants within these genes are under natural selection and may be more likely to influence melanoma." (PMID 32241263, 2020).
sensorineural hearing loss (1 paper, 2025). "We also examine the contributions of genes such as TECTA, TECTB, and CEACAM16, whose mutations disrupt TM integrity and lead to sensorineural hearing loss." (PMID 40901670, 2025).
Tumor (1 paper, 2017). "Also, the availability of patient DNA from the non tumoral tissue highlighted that the SNVs identified in the tumor tissue and Chor-IN-1 cell line were mainly germline, with four exceptions involving TECTA, SART3, KEL and MUC1 genes." (PMID 28835717, 2017).
TECTA also shares sentences with these, for which no sentence is quoted: Hearing impairment (3 papers); autosomal recessive deafness (2); Vertigo (2); Arrhythmogenic right ventricular dysplasia (1); autism (1); Birk-Barel syndrome (1); cancer (1); Chediak-Higashi syndrome (1); Cohen syndrome (1); Escobar syndrome (1); hyperthyroidism (1); nonsyndromic hearing loss (1); Rubinstein-Taybi syndrome 1 (1); Stargardt disease (1); temtamy syndrome (1); Wolfram syndrome (1).